SLC71A1 (solute carrier family 71 member 1)
Description:
Probable membrane-bound transporter. May play a role in neuronal nutrient sensing and energy homeostasis. Required for the final stages of spermatogenesis.
Synonyms: HIAT1; MFSD14A; DKFZP564L0864; HAIT1
Tractability: Antibody: UniProt predicts a signal peptide or a membrane-spanning region. PROTAC: ubiquitination databases record sites on it.
Gene: Protein-coding gene on chromosome 1 (100,038,076 to 100,083,945, forward strand). Ensembl gene ENSG00000156875.
Subcellular location: Membrane
Subcellular location (Human Protein Atlas): Vesicles
Gene Ontology:
Molecular function: transmembrane transporter activity
Biological process: transmembrane transport
Cellular component: Golgi membrane; membrane
Genetic constraint (gnomAD): Loss-of-function variants: 15 observed, 28.4 expected, observed/expected ratio (o/e) 0.53, 90% interval 0.35 to 0.81. The upper end of that interval is the gene's LOEUF score, 0.81, which puts it in group 3 of 6, group 1 being the genes least tolerant of losing a copy. Missense variants: 261 observed, 386.31 expected, observed/expected ratio (o/e) 0.68, 90% interval 0.61 to 0.75. Synonymous variants: 151 observed, 145.35 expected, observed/expected ratio (o/e) 1.04, 90% interval 0.91 to 1.19.
Homologues: Orthologues: mouse Mfsd14a (99% identical), rabbit MFSD14A (99% identical), dog MFSD14A (99% identical), guinea pig MFSD14A (99% identical), rat Mfsd14a (99% identical), chimpanzee MFSD14A (97% identical), macaque SLC35A3 (97% identical), tropical clawed frog mfsd14a (93% identical), pig MFSD14A (89% identical), zebrafish mfsd14a1 (86% identical), Drosophila melanogaster CG11537 (57% identical), Caenorhabditis elegans T25D3.4 (54% identical), and 12 more. Paralogues in human: SLC71A2 (73% identical), SLC75A1 (20% identical), SLC67A2 (18% identical), MFSD1 (15% identical), MFSD8 (15% identical), SLC61A1 (13% identical).
Diseases named in the same sentence as SLC71A1 in open-access papers:
SLC71A1 is named in the same sentence as 6 diseases in open-access papers, as found by Europe PMC text mining. Sharing a sentence is not in itself a finding about the gene and the disease.
SLC71A1 shares sentences with these, for which no sentence is quoted: clear cell renal cell carcinoma (3 papers); tumor (3); infertile (2); bladder carcinoma (1); gastric cancer (1); type 2 diabetes (1).